SP100 (SP100 nuclear body protein)
Diseases named in the same sentence as SP100 in open-access papers (continued):
Sharing a sentence is not in itself a finding about the gene and the disease.
leukemia (5 papers, 2012 to 2025). A malignant (clonal) hematologic disorder, involving hematopoietic stem cells and characterized by the presence of primitive or atypical myeloid or lymphoid cells in the bone marrow and the blood. "SP100 is a subunit of promyelocytic leukemia nuclear bodies (PML-NBs) and binds to heterochromatin protein 1 (HP1), contributing to transcriptional repression and chromosomal architecture." (PMID 41188771, 2025). "Regarding B cells, ATLL IgG strongly recognized proteins like SP110 and SP100, which are linked to B cell survival, NCOA3, associated with leukemia development, and BCAS4, related to cancer progression." (PMID 41303346, 2025). "SP100 and ZNF451 are both components of promyelocytic leukemia (PML) bodies, which are implicated in interferon-induced antiviral defenses." (PMID 22291592, 2012).
cholestasis (4 papers, 2022 to 2025). Impairment of the bile flow caused by obstruction within the liver, or outside the liver in the bile duct system. "In this study, we found that exosomal miR-122-5p is associated with liver injury and cholestasis indicators, and the combination of gp210 and sp100 antibodies can improve the sensitivity of PBC diagnosis." (PMID 41246340, 2025). "EASL recommends that, in the correct context, a diagnosis of AMA-negative PBC can be made in patients with cholestasis and ANA-specific immuno-fluorescence (nuclear dots or perinuclear rims) or ELISA (using sp100 or gp210 antibodies)." (PMID 35453551, 2022).
autoimmune disease (3 papers, 2020 to 2025). A disorder resulting from loss of function or tissue destruction of an organ or multiple organs, arising from humoral or cellular immune responses of the individual to their own tissue constituents. "Speckled 100 kDa protein (Sp100) was identified using autoantibodies from patients suffering from primary biliary cirrhosis autoimmune disease." (PMID 33598438, 2020). "However, in nearly all AMA-negative PBC patients, it is possible to find other PBC-specific antinuclear antibodies, such as anti-sp100 and anti-glycoprotein-210 antibodies, confirming PBC as an autoimmune disease." (PMID 33917502, 2021).
laryngeal carcinoma (3 papers, 2020 to 2025). Carcinoma that arises from the laryngeal epithelium. "It was found that high expression of SP100 was associated with poor cell differentiation in laryngeal cancer." (PMID 32431729, 2020). "SP100 expression was reported in 11 studies across cancers, including HCC, lung cancer, breast cancer, PAAD, glioma, mantle cell lymphoma, laryngeal cancer, CRC, and ccRCC." (PMID 41188771, 2025).
leiomyosarcoma (3 papers, 2018 to 2024). An uncommon, aggressive malignant smooth muscle neoplasm, usually occurring in post-menopausal women. "Consistent with this expectation, an integrative genome and transcriptome analysis of leiomyosarcoma applied TelNet for the TMM annotation and identified recurrent mutations in RBL2 (RB transcriptional corepressor like 2) and SP100 (SP100 nuclear antigen) as linked to ALT." (PMID 29776332, 2018). "These tumors lacked PRC2 (EED, SUZ12) mutations, and no mutations were present in RBL2 or SP100, two altered telomere maintenance genes found to be enriched in ALT-positive leiomyosarcomas." (PMID 31462295, 2019).
Liver Diseases (3 papers, 2012 to 2026). "We report the case of a female patient presenting with a cholestatic liver disease and a panel of autoantibodies specific for PBC, including antibodies to mitochondrial E2-pyruvate dehydrogenase, gp-210 and Sp-100." (PMID 23226177, 2012).
melanoma (3 papers, 2017 to 2024). A malignant, usually aggressive tumor composed of atypical, neoplastic melanocytes. "Only the module turquoise had a significant enrichment (p = 0.009) of genes whose homologs displayed prognostic value in melanoma, such as Oca2, Samhd1, Nlrc5, Irf1, Ifitm3, Sp100, Dram1, Rtn1, Tcaf2, Parp10, and Grin3a." (PMID 32831131, 2020). "Moreover, Irf1, Ifitm3, and Sp100 are involved in the interferon-mediated response that plays a role in antitumor immunity in melanoma." (PMID 32831131, 2020).
COVID-19 (2 papers, 2023 to 2024). A disease caused by infection with severe acute respiratory syndrome coronavirus 2. "In addition, we found that some TFs were differentially expressed in severe COVID-19, including TF upregulations of IRF7, SP100, HMGB2, and BCL6, and downregulations of FOS and JUNB." (PMID 38612651, 2024).
Hepatic failure (2 papers, 2022 to 2025). "Age, IL-2, ALB, γ-GT, ALP, TBIL, Hb, TBA, WBC, and PLT, as well as anti-Sp100, were found to be independent risk factors in PBC patients with liver failure." (PMID 36159788, 2022). "Univariate analysis revealed that the incidence of liver failure was remarkably associated with age, IL-2, γ-GT, TBIL, WBC, and anti-Sp100." (PMID 36159788, 2022). "Moreover, multivariate analysis showed that age(P=0.023), IL-2(P=0.023), TBIL(P=0.001), and anti-SP100(P=0.001) were independent predictors of the development of liver failure." (PMID 36159788, 2022).
herpesvirus infection (2 papers, 2011 to 2016). "ICP0 induces the degradation or disrupts the functions of several PML NB components, for example, PML, Sp100, hDaxx, and ATRX (12, –, 16), each of which has been shown to have a role in restricting herpesvirus infections." (PMID 27535048, 2016). "Cellular restriction factors responding to herpesvirus infection include the ND10 components PML, Sp100 and hDaxx." (PMID 21698222, 2011). "With the advent of RNA interference (RNAi)-mediated depletion methodologies, it became apparent that Sp100 acts as a repressor rather than an activator in several herpesvirus infections, and the activation seen in earlier studies may be explained by dominant negative effects due to overexpression." (PMID 27535048, 2016).
Hypertension (2 papers, 2023 to 2024). The presence of chronic increased pressure in the systemic arterial system. "Our findings confirm and expand upon previous observations, as we discovered that the presence of anti-sp100 antibodies was associated with liver-related adverse outcomes in PBC patients who also had the metabolic risk factor of hypertension at baseline, as shown by univariate analysis." (PMID 38027142, 2023). "Additionally, anti-sp100 was associated with adverse outcomes (P=0.013) in PBC patients with hypertension in univariate Cox regression analysis." (PMID 38027142, 2023). "In this study, it was observed that patients with both PBC and hypertension had significantly worse prognoses when also presenting with anti-sp100." (PMID 38027142, 2023). "However, it was observed that anti-sp100 was a distinctive risk factor that had a statistically significant association with adverse outcomes, but only in the PBC plus hypertension group (P=0.013, HR: 2.686, 95% CI:1.230–5.868)." (PMID 38027142, 2023). "Anti-sp100 might be associated with adverse outcomes, especially in PBC patients with hypertension." (PMID 38027142, 2023). "We then further divided them into anti-sp100 positive and negative groups to investigate the impact of hypertension on anti-sp100." (PMID 38027142, 2023). "However, we did not observe significant associations between anti-sp100 antibodies and adverse outcomes in PBC patients without hypertension at baseline." (PMID 38027142, 2023).
ocular melanoma (2 papers, 2024 to 2025). A melanoma that arises from the structures of the eye or ocular adnexa. "Interestingly, combining these multiomics data, we noticed that nuclear autoantigen speckled protein 100 (SP100) was upregulated at both the mRNA and protein levels after silencing ALKBH3 in ocular melanoma cells, following a dramatic change in the m1A modification level." (PMID 38118002, 2024).
pancreatic adenocarcinoma (2 papers, 2023 to 2025). "While SP100 acts as a tumor suppressor in malignancies like breast cancer, SP110 and SP140 are implicated in promoting oral squamous cell carcinoma and glioma progression, respectively, and SP140L is linked to poor prognosis in pancreatic adenocarcinoma." (PMID 41188771, 2025).
Sepsis (2 papers, 2020 to 2022). Sepsis is defined as life-threatening organ dysfunction caused by a dysregulated host response to infection. "Despite epidemiological research linking sepsis and cancer, including acute and chronic leukemia, more studies are needed to verify the function of SP100 in sepsis and septic cardiomyopathy." (PMID 35971449, 2022).
adenovirus infection (1 paper, 2017). "Correspondingly, the SAND domain containing isoforms of Sp100 also function as repressors of HSV immediate-early transcription and adenovirus infection." (PMID 28968443, 2017).
alpha thalassemia/mental retardation syndrome X-linked (1 paper, 2021). "IFI16 forms filamentous structures on HSV DNA that recruit components of PML-NB including PML, speckled 100 kDa (SP100) and alpha thalassemia/mental retardation syndrome X-linked (ATRX), to increase repression of viral gene expression." (PMID 34676800, 2021).
embryonal carcinoma (1 paper, 2015). A non-seminomatous malignant germ cell tumor characterized by the presence of large germ cells with abundant cytoplasm resembling epithelial cells, geographic necrosis, high mitotic activity, and pseudoglandular and pseudopapillary structures formation. "This was important since the embryonal carcinoma cell line NT2, which has been used by a number of laboratories to study latency possesses abnormal ND10 structures resulting from lower expression of the structure defining protein PML and the complete loss of Sp100." (PMID 26057166, 2015).
HIV-1 infection (1 paper, 2019). The type species of lentivirus and the etiologic agent of acquired immunodeficiency syndrome (AIDS). "Moreover, certain ‘common ISGs’ that were upregulated by HIV-1 infection (IRF7, TRIM25, MYD88, MX2, LGALS9, and SP100) exhibited a strong anti-HIV-1 effect in THP-1 cells." (PMID 30915053, 2019).
liver cirrhosis (1 paper, 2023). "After adjusting for age, gender, T.Bil, ALP, Sp100, and gp210, IIF-AMA (OR: 3.05, 95% CI: 1.59–5.87), AMA-M2 (OR: 3.11, 95% CI: 1.61–6.01), and M2-3E (OR: 3.29, 95% CI: 1.63–6.66) remained significantly associated with an increased liver cirrhosis incidence." (PMID 37861502, 2023). "After adjusting for age, gender, T.Bil, and ALP, it was found that neither Sp100 nor gp210 were related to liver cirrhosis." (PMID 37861502, 2023).
lung carcinoma (1 paper, 2025). "Lung cancer mirrored this, with high SP100 and SP140 expression linked to better prognosis, involving apoptotic (TNF-α, caspase) and TAM-mediated immune pathways, respectively." (PMID 41188771, 2025). "SP100 exhibited context-dependent roles: high expression correlated with better prognosis in breast/lung cancers but poorer outcomes in glioma/PAAD, while low expression in LSCC was linked to tumorigenesis." (PMID 41188771, 2025). "In solid tumors, this review uncovers novel tissue-specific roles: SP140 promotes glioma progression but protects osteosarcoma, while SP100 suppresses breast and lung cancers yet exacerbates PAAD." (PMID 41188771, 2025). "High SP100 expression was observed in breast cancer, lung cancer, glioma, and PAAD." (PMID 41188771, 2025).
metastatic cancers (1 paper, 2019). A carcinoma which has spread from the original site of growth to another anatomic site. "As with SP100 and TGFB3 as markers of Gleason score, the false negative rate for using LMNA positioning as a marker of non-metastatic cancer was high at 42.9% (3/7), and the false positive rate is relatively low at 8.3% (1/12)." (PMID 31681438, 2019).
metastatic melanoma (1 paper, 2024). A melanoma that has spread from its primary site to another anatomic site. "Consistently, ALKBH3 exhibited a significant negative correlation with SP100 in a group of 87 metastatic melanoma samples (deposited in GEO database: GSE7553, R = –0.227, P= 0.035)." (PMID 38118002, 2024).
prostate carcinoma (1 paper, 2019). A carcinoma that arises from epithelial cells of the prostate gland. "Even so, the false positive rates of detecting low Gleason score prostate cancers were low because the direction of repositioning for SP100 and TGFB3 was mostly specific to the subgroups." (PMID 31681438, 2019). "We also selected SP100 to test its potential as a marker of low risk, since we previously found it to reposition in a low risk Gleason score 6 prostate cancer, but not in three intermediate or high-risk Gleason score 7 cancers." (PMID 31681438, 2019). "However, most of the evidence for PML bodies role in cancer relates to the PML protein, not SP100, which has not been implicated in prostate cancer." (PMID 31681438, 2019). "We find that directional repositioning of SP100 and TGFB3 gene loci stratifies prostate cancers of differing Gleason scores." (PMID 31681438, 2019). "Positioning patterns for SP100 and TGFB3 by prostate cancer subgroups." (PMID 31681438, 2019). "We find that SP100 and TGFB3 occupy alterative positions in low Gleason score cancers compared to higher Gleason scored cancers, and that LMNA repositions more internally in many non-metastatic and low risk prostate cancers, but infrequently reposition in high risk/aggressive cancers." (PMID 31681438, 2019). "Interestingly, for SP100 and TGFB3 it was not the repositioning itself, but the direction of repositioning that was useful for stratification of prostate cancers." (PMID 31681438, 2019).
rheumatic disease (1 paper, 2024). "Finding anti-sp100 and anti-sp210 is not always easy as they are sometimes not visible on Hep2 cells or because the ANA visualisation can be hindered by the AMA presence or other ANA specificities, often seen in patients with the rheumatic disease." (PMID 39272667, 2024).
infection (38 papers, 2009 to 2025). The state of being infected such as from the introduction of a foreign agent such as serum, vaccine, antigenic substance or organism. "Quantitative reverse transcription PCR (RT-qPCR) analysis showed significant upregulation of PML isoforms and PML-NB-associated genes (Daxx and SP100) at 36 and 48 h post-infection (hpi)." (PMID 34888375, 2021). "In summary, Sp100 associates with replication foci at late times in infection and appears to repress this stage of infection by binding to viral chromatin." (PMID 28968443, 2017). "In a similar fashion, the vFGARAT of RRV, ORF75, induces degradation of both PML and SP100 upon recombinant expression, and infection with RRV leads to an almost complete loss of these ND10 components in infected cells." (PMID 29065450, 2017). "The HSV-1 immediate-early protein ICP0, a viral ubiquitin E3 ligase, degrades both PML and SP100 during infection, which facilitates efficient HSV-1 replication." (PMID 39823515, 2025). "Key regulatory genes such as IFI16, IFITM1, and SP100 show exceptionally high degrees of connectivity, indicating their central role in the immediate host response to the infection." (PMID 39591472, 2024). "For instance, PML and SUMO-1 were reported to be associated with PML NBs during the whole course of infection, whereas Sp100 and Daxx dissociated from NBs in the late phase of infection." (PMID 37127643, 2023). "Nevertheless, one PML NB component, Sp100, has been shown to restrict viral transcription and replication in the later stages of infection." (PMID 37127643, 2023). "Agreeably, knocking down expression of individual PML NB components such as PML, Daxx, and Sp100 in primary human fibroblasts showed a de-repressing effect on HCMV IE gene expression at low multiplicity of infection." (PMID 34513832, 2021). "It has been demonstrated that Sp100 restricts HPV18 early transcription during establishment of infection." (PMID 30802273, 2019). "Analysis of Sp100 binding to viral chromatin showed that Sp100 bound across the viral genome, and that binding increased at late stages of infection." (PMID 28968443, 2017). "In summary, we have shown that Sp100 represses viral replication and transcription at early and late stages of infection." (PMID 28968443, 2017). "Sp100 proteins limit the transcription and replication of many viruses, often by repressing incoming genomes at the early stages of infection." (PMID 28968443, 2017). "An elegant study by Gunther and colleagues revealed that the PML factor Sp100 is involved in the regulation of the H3K27me3 level on lytic promoters during de novo infection." (PMID 27606464, 2016). "Our results were consistent with the reported degradation of RIG-I and of the nuclear HCMV restriction factor Sp100 during infection (respectively)." (PMID 24906157, 2014). "Instead, we observed that total Sp100 protein levels exhibited a mild increase at 8 and 24 hours post infection, but had returned to baseline levels at the 48 h time point." (PMID 25033267, 2014). "This is consistent with the observation that Sp100 foci are increased in number and volume at 72 h post infection, at a time point when the (likely interferon induced) mild increase of total Sp100 protein levels has abated." (PMID 25033267, 2014). "Surprisingly, we observed that KSHV infection resulted in the complete removal of Sp100 from soluble extracts at 48 h post infection." (PMID 25033267, 2014). "The time course experiment confined the disappearance of soluble Sp100 to a time period between 24 and 48 h post infection." (PMID 25033267, 2014). "Early during infection, ICP0 colocalizes with PML and induces the proteasomal degradation of PML as well as the loss of certain forms of Sp100." (PMID 25513827, 2014).